OVOL2 (ovo like zinc finger 2)
Description:
Zinc-finger transcription repressor factor. Plays a critical role in maintaining the identity of epithelial lineages by suppressing epithelial-to mesenchymal transition (EMT) mainly through the repression of ZEB1, an EMT inducer (By similarity). Positively regulates neuronal differentiation (By similarity). Suppresses cell cycling and terminal differentiation of keratinocytes by directly repressing MYC and NOTCH1. Important for the correct development of primordial germ cells in embryos (By similarity). Plays dual functions in thermogenesis and adipogenesis to maintain energy balance. Essential for brown/beige adipose tissue-mediated thermogenesis, is necessary for the development of brown adipocytes. In white adipose tissues, limits adipogenesis by blocking CEBPA binding to its transcriptional targets and inhibiting its transcription factor activity (By similarity).
Synonyms: hOvo2; ZNF339; bA504H3.3; CHED; CHED1; CHED2; EUROIMAGE566589; PPCD1
Tractability: No criterion of Open Targets' tractability assessment is met for any kind of drug.
Gene: Protein-coding gene on chromosome 20 (17,956,979 to 18,059,188, reverse strand). Ensembl gene ENSG00000125850.
Subcellular location: Nucleus
Subcellular location (Human Protein Atlas): Nucleoplasm; Cytosol
Gene Ontology:
Molecular function: protein binding; sequence-specific double-stranded DNA binding; DNA-binding transcription factor activity, RNA polymerase II-specific; DNA-binding transcription repressor activity, RNA polymerase II-specific; RNA polymerase II cis-regulatory region sequence-specific DNA binding; transcription corepressor activity; chromatin binding; DNA binding; DNA-binding transcription activator activity, RNA polymerase II-specific
Biological process: epidermal cell differentiation; negative regulation of epithelial to mesenchymal transition; negative regulation of gene expression; negative regulation of SMAD protein signal transduction; negative regulation of transforming growth factor beta receptor signaling pathway; negative regulation of white fat cell proliferation; positive regulation of brown fat cell differentiation; positive regulation of cold-induced thermogenesis; positive regulation of gene expression; regulation of transcription by RNA polymerase II; negative regulation of cell differentiation; negative regulation of DNA-templated transcription; negative regulation of multicellular organismal process; negative regulation of signal transduction; negative regulation of transcription by RNA polymerase II; positive regulation of transcription by RNA polymerase II; regulation of keratinocyte differentiation; regulation of keratinocyte proliferation
Cellular component: nucleus
Genetic constraint (gnomAD): Loss-of-function variants: 13 observed, 16.97 expected, observed/expected ratio (o/e) 0.77, 90% interval 0.5 to 1.22. The upper end of that interval is the gene's LOEUF score, 1.22, which puts it in group 5 of 6, group 1 being the genes least tolerant of losing a copy. Missense variants: 335 observed, 328.21 expected, observed/expected ratio (o/e) 1.02, 90% interval 0.93 to 1.12. Synonymous variants: 166 observed, 146.79 expected, observed/expected ratio (o/e) 1.13, 90% interval 1 to 1.29.
Homologues: Orthologues: chimpanzee OVOL2 (99% identical), macaque OVOL2 (99% identical), pig OVOL2 (89% identical), mouse Ovol2 (89% identical), rat Ovol2 (89% identical), dog OVOL2 (82% identical), rabbit OVOL2 (80% identical), guinea pig OVOL2 (80% identical), tropical clawed frog ovol2 (60% identical), zebrafish zgc:171929 (20% identical), Drosophila melanogaster CG12391 (17% identical), Drosophila melanogaster hb (17% identical), and 2 more. Paralogues in human: OVOL1 (51% identical), OVOL3 (35% identical), ZNF641 (23% identical), ZKSCAN2 (21% identical), ZNF18 (20% identical), PEG3 (20% identical), ZSCAN29 (20% identical), ZSCAN32 (20% identical), ZBTB35 (20% identical), ZNF518A (19% identical), ZSCAN5A (19% identical), PLAGL2 (19% identical), and 17 more.
Diseases named in the same sentence as OVOL2 in open-access papers:
OVOL2 is named in the same sentence as 37 diseases in open-access papers, as found by Europe PMC text mining. Sharing a sentence is not in itself a finding about the gene and the disease. The quoted sentences say what the papers report.
breast carcinoma (16 papers, 2016 to 2024). "Overall, these findings establish the suppressive role of OVOL2 in breast cancer progression, and its loss leads to an increase in the malignancy of breast tumors." (PMID 38627980, 2024). "These indicate that loss of OVOL2 promotes fatty acid oxidation that supports breast cancer stemness properties might though upregulating CPT1 expression." (PMID 38627980, 2024). "In summary, our study reveals a novel mechanism of OVOL2 as a tumor suppressor in breast cancer, inhibiting tumor stemness and metastasis through STAT3 signaling pathway and FAO inhibition." (PMID 38627980, 2024). "Overexpression of OVOL2 in TNBC cell lines reduced breast cancer stemness characteristics including cell proliferation and sphere formation both in vitro and in vivo." (PMID 38627980, 2024). "We also analyzed mRNA levels of OVOL2 in breast cancer cell lines by quantitative reverse transcription‐PCR (RT‐qPCR)." (PMID 38627980, 2024). "ZNF750 was recently described as an EMT repressor in breast cancer, an activity shared by OVOL2, TP63, and FOXO1." (PMID 38066300, 2023). "Ovo Like Zinc Finger 2 (OVOL2), a transcription factor, inhibits the Warburg effect and breast cancer progression by suppressing the expression of glycolytic genes." (PMID 36900384, 2023). "We found that OVOL2 protein expression was significantly downregulated in breast cancer tissues when compared with normal tissues." (PMID 35896951, 2022). "Glycolysis is critical for OVOL2‐mediated regulation of breast cancer cell proliferation, invasion and metastasis." (PMID 35896951, 2022). "OVOL2 expression is negatively correlated with glycolytic gene expression and can be a good predictor of prognosis in patients with breast cancer." (PMID 35896951, 2022). "External datasets from TCGA (The Cancer Genome Atlas) revealed that OVOL2 mRNA expression was significantly upregulated in breast cancer tissues when compared with that observed in normal tissues." (PMID 35896951, 2022). "In epithelial tumors, such as colorectal cancer, breast cancer and lung adenocarcinoma, several studies have demonstrated that OVOL2 suppress invasion capability by inhibiting EMT and OVOL2 protein expression level is related with patient’s prognosis." (PMID 34117242, 2021). "OVOL2 has been implicated in the regulation of EMT process in the mouse mammary gland and human breast cancer cells through the transcriptional inhibition of ZEB1." (PMID 28455959, 2017). "Along with the progression of breast cancer, OVOL2 expression is downregulated, resulting in its inability to inhibit TGF-β signaling." (PMID 28455959, 2017). "Our study reveals a complex association between OVOL2 and the central EMT signaling pathway, which highlights the role of OVOL2 in the regulation of breast cancer malignant phenotypes." (PMID 28455959, 2017). "Expression of the transcription factors OVOL1 and OVOL2 in mesenchymal prostate cancer and poorly differentiated breast cancer cells induces MET and so inhibits their metastatic potential." (PMID 27144453, 2016). "Moreover, our findings revealed that OVOL2 regulates breast cancer cell migration and metastasis, as well as modulates breast cancer cell proliferation in vitro and breast tumor growth in vivo." (PMID 35896951, 2022). "OVOL2 could inhibit glycolytic gene expression, glycolysis and breast cancer cell proliferation, invasion and metastasis in vitro and in vivo, mainly through NCoR." (PMID 35896951, 2022). "The modulation of these molecular processes may represent a strategy for inhibiting breast cancer invasion by restoring OVOL2 expression." (PMID 28455959, 2017). "Since OVOL2 expression in breast cancer specimens progressively declines due to its promoter methylation (unpublished data), we reason that OVOL2 might contribute to TGF-β inhibition in early stage of cancers." (PMID 28455959, 2017).
breast carcinoma (continued). "Therefore, we cannot exclude the possibility that OVOL2 may affect lipid catabolism in breast cancer cells by modulating the activity of the TNF pathway." (PMID 38627980, 2024). "As Ovol2 is significantly downregulated in claudin-low-type breast cancers, this suggests that cell identity-related disruptions within the basal cell compartment may also contribute to subtype specification during breast cancer development." (PMID 27110512, 2016). "Our results demonstrated that OVOL2 deletion promotes tumor initiation in MMTV‐PyVT mice via the regulation of FAO, thus implicating the potential clinical value of FAO inhibitors for breast cancer treatment." (PMID 38627980, 2024). "To further explore the physiological role of OVOL2 in breast cancer, we generated MMTV‐PyVT, MMTV‐Cre Ovol2 f/f mice (PyVT‐Ovol2KO)." (PMID 38627980, 2024). "We confirmed the specificity of OVOL2, PKM2, and LDHA antibodies by immunohistochemical staining of breast cancer tissues or immunoblotting with cell lysates." (PMID 35896951, 2022). "Patients with breast cancer exhibiting low OVOL2 expression had shorter disease‐free survival (DFS) and overall survival (OS) than those with high OVOL2 expression." (PMID 35896951, 2022). "In current study, we establish the relationship between OVOL2 expression and EMT phenotype or tumor progression by checking breast cancer cell lines and patients cohorts in the public databases." (PMID 28455959, 2017). "Two recent studies demonstrate that OVOL2 inhibits EMT in the mouse mammary gland and human breast cancer cells through the transcriptional inhibition of ZEB1." (PMID 28455959, 2017). "In the present study, we demonstrated that OVOL2, a zinc finger transcription factor, inhibits TGF-β signaling-induced EMT in mouse and human mammary tumor cells, as well as in mouse tumor models." (PMID 28455959, 2017). "Herein, we provide evidence to demonstrate that OVOL2 antagonizes TGF-β signaling at multiple levels of the signaling cascade, resulting in the inhibition of EMT during mammary tumor metastasis." (PMID 28455959, 2017). "Triple‐negative breast cancer (TNBC), the most aggressive breast cancer subtype, exhibits downregulated expression of the epithelial transcription factor OVOL2." (PMID 38627980, 2024). "Studies in breast cancer have found that Ovol2 inhibits EMT by direct transcriptional inhibition of ZEB1 expression, and studies in liver cancer have shown that Ovol2 inhibits EMT by indirectly promoting miR-200 expression, and that targeting TRPV1 can inhibit EMT by affecting the Ovol2-zeb1 axis." (PMID 35346238, 2022). "Moreover, OVOL2 overexpression repressed glucose uptake and lactate production in ZR75‐1 and MDA‐MB‐231 breast cancer cells." (PMID 35896951, 2022). "We also utilized mesenchymal-like MDA-MB-231 human breast cancer cells, in which TGF-β signaling is aberrantly activated, to determine whether OVOL2 also inhibits EMT phenotypes in MDA-MB-231 cells." (PMID 28455959, 2017). "Data from the Oncomine databases indicated a strong negative relationship between OVOL2 expression and breast cancer progression." (PMID 28455959, 2017). "Unexpectedly, similar to the well‐known hypoxia‐inducible protein, hypoxia‐inducible factor 1α (HIF1α), hypoxia could induce the expression of OVOL2 protein in MCF7, ZR75‐1 and MDA‐MB‐231 breast cancer cells, suggesting that OVOL2 expression is regulated at the protein level." (PMID 35896951, 2022). "However, regulation of the EMT process by OVOL2 in breast cancer is not completely defined." (PMID 28455959, 2017). "Our findings uncover the regulatory mechanism by which OVOL2 represses FAO in breast cancer and propose that targeting JAK/STAT3‐FAO is a potential strategy for OVOL2‐absent TNBC therapy." (PMID 38627980, 2024).
breast carcinoma (continued). "Hence, the regulation of E-cadherin could involve OVOL2 but not ZEBs in breast cancer cells." (PMID 36768838, 2023). "Given the unavailability of data for OVOL2 protein expression in normal breast tissues from external Clinical Proteomic Tumor Analysis Consortium (CPTAC) datasets, we could not compare OVOL2 expression between breast cancer tissues and normal breast tissues." (PMID 35896951, 2022).
colorectal cancer (7 papers, 2019 to 2024). A primary or metastatic malignant neoplasm that affects the colon or rectum. "Similarly, the OVOL2 promoter is hypermethylated in late-stage colorectal cancer cells, resulting in OVOL2 suppression." (PMID 39409910, 2024). "OVOL2 was recently revealed as a transcriptional repressor of EMT through downregulating ZEB1 and TWIST in various cancer types such as in lung, breast, and colorectal cancers." (PMID 31404945, 2019).
prostate carcinoma (5 papers, 2013 to 2025). A carcinoma that arises from epithelial cells of the prostate gland. "We recently demonstrated a novel function of the OVOL1 (ovo-like 1, Entrez GeneID 5017) and OVOL2 (ovo-like 2, GeneID 58495) TFs as critical inducers of MET in prostate cancer." (PMID 24612742, 2014). "We demonstrated that in primary tumors of prostate cancer patients the expression of OVOL1 and OVOL2 highly correlate with E-cad expression, a critical marker of the differentiation state of these tumors." (PMID 24124593, 2013). "In the prostate cancer model, we analyzed the following cell lines: PC3-EMT14-OVOL1 (OVOL1 overexpression), PC3-EMT14-OVOL2 (OVOL2 overexpression) and PC3-Epi (epithelial cells that express OVOL1 and OVOL2 and from which the mesenchymal PC3-EMT14 were initially obtained)." (PMID 24612742, 2014).
lung carcinoma (4 papers, 2022 to 2024). "The low expression level of OVOL2 in lung cancer can increase tumorigenesis, while upregulated OVOL2 reduces the survival of cancer cells." (PMID 39014491, 2024). "Through Western blot analysis, we found that OVOL2 expression was lower in murine lung cancer tissue derived from KrasG12D mice than in normal lung tissue." (PMID 35346238, 2022). "Previous studies have confirmed that OVOL2 plays an important role in tumor development and metastasis, including in lung cancer." (PMID 35346238, 2022). "A study in lung cancer found that Ovol2 inhibits EMT through direct transcriptional inhibition of Twist1 expression." (PMID 35346238, 2022). "Therefore, identifying the molecular mechanism by which OVOL2 regulates this process is crucial for understanding the biological functions of OVOL2 in lung cancer." (PMID 35346238, 2022). "We also examined the protein expression level of OVOL2 in a KrasG12D-based lung cancer mouse model." (PMID 35346238, 2022). "Since NF-κB is a dominant oncogene in NSCLC and plays an important role in glucose metabolism homeostasis, manipulating the interaction between NF-κB and OVOL2 may constitute a new therapeutic approach for lung cancer." (PMID 35346238, 2022). "However, the function of OVOL2 in regulating glucose metabolism in lung cancer cells has not been elucidated." (PMID 35346238, 2022).
breast tumor (3 papers, 2017 to 2024). "Furthermore, treatment with FAO inhibitors effectively reduces stemness characteristics of tumor cells, breast tumor initiation, and metastasis, especially in OVOL2‐deficient breast tumors." (PMID 38627980, 2024). "Specifically, the secondary transplantation experiment revealed that the loss of OVOL2 in mouse breast tumor cells resulted in enhanced and more stable tumor‐initiating capacity, further highlighting the crucial role of OVOL2 in regulating CSC properties in vivo." (PMID 38627980, 2024). "Herein, the transcription factor OVO‐like zinc finger 2 (OVOL2) is demonstrated to directly repress the expression of several glycolytic genes, blocking the Warburg effect and breast tumor growth and metastasis in vitro and in vivo." (PMID 35896951, 2022). "Consistent with cell proliferation and invasion results in vitro, OVOL2 overexpression inhibited breast tumor growth and metastasis in nude mice, whereas NCoR KD promoted breast tumor growth and metastasis." (PMID 35896951, 2022). "Moreover, patients with breast tumors exhibiting increased glucose uptake, as assessed by 18F‐fluoro‐2‐deoxy‐D‐glucose positron emission tomography (18FDG PET) scans, revealed reduced OVOL2 expression." (PMID 35896951, 2022). "Notably, the absence of OVOL2 makes TNBC and primary breast tumors become more reliant on fatty acid oxidation to sustain rapid growth and tumor progression." (PMID 38627980, 2024).
colon cancer (3 papers, 2022 to 2023).
corneal endothelial dystrophies (3 papers, 2016 to 2024). "We show that variants in the OVOL2 promoter sequence cause the spectrum of phenotypes observed in over 100 affected individuals, implicating perturbed transcriptional regulation of OVOL2 as a major cause of dominant corneal endothelial dystrophies." (PMID 26749309, 2016). "Notably, the breakpoint on chromosome 20 was identified to lie within the same topologically associated domain (TAD) as corneal endothelial dystrophy-associated gene OVOL2, and it is predicted to disrupt distal enhancers." (PMID 40225920, 2024). "However, perturbed transcriptional regulation of OVOL2 has been implicated as a major cause of dominant corneal endothelial dystrophies." (PMID 38785568, 2024). "We also evaluated the possible pathogenicity of variants in genes known to be associated with congenital or childhood-onset monogenic corneal endothelial dystrophies (i.e., GRHL2, ZEB1, and OVOL2)." (PMID 40225920, 2024). "Disruption of a candidate cis-regulatory element and/or positional effects induced by translocation of OVOL2 to a novel genomic context may lead to an aberrant OVOL2 expression, a previously characterized disease mechanism of corneal endothelial dystrophy." (PMID 40225920, 2024).
nasopharyngeal carcinoma (3 papers, 2020 to 2024). A carcinoma arising from the nasopharyngeal epithelium. "Furthermore, nasopharyngeal carcinoma cells have decreased levels of OVOL2 and E-cadherin and increased levels of N-cadherin compared to normal nasopharyngeal epithelial cells, and the low levels of OVOL2 are a result of hypermethylation at the promoter region." (PMID 39409910, 2024). "Feng and colleagues describe the role of ZNF339 (OVOL2), a member of the Ovo family of conserved zinc-finger transcription factors, in metastasis and the enrichment of stemness in nasopharyngeal carcinoma." (PMID 32089740, 2020).
hepatocellular carcinoma (2 papers, 2020 to 2022). A malignant tumor that arises from hepatocytes. "Thus, elevated OVOL2 expression might suppress hepatocellular carcinoma cell invasion and metastasis by restricting EMT." (PMID 32106476, 2020).
posterior polymorphous corneal dystrophy (2 papers, 2017 to 2022). Posterior polymorphous corneal dystrophy (PPCD) is a rare mild subtype of posterior corneal dystrophy characterized by small aggregates of apparent vesicles bordered by a gray haze at the level of Descemet membrane, generally with no effect on vision. "They show phenotypic overlap with posterior polymorphous corneal dystrophy (PPCD) caused by pathogenic variants in OVOL2, ZEB1, and GRHL2, but no genetic cause for PCVs has been identified, although an association with x-linked megalocornea was noted in one case." (PMID 36079096, 2022).